APOE (apolipoprotein E)
Diseases named in the same sentence as APOE in open-access papers (continued):
Sharing a sentence is not in itself a finding about the gene and the disease.
dyslipidemia (continued). "ApoE is involved in the lipid metabolism and conversion of lipoproteins and is a critical factor in various cardiovascular and neurodegenerative conditions, including cerebral infarction and dyslipidemia." (PMID 40867851, 2025). "Our results suggest that GLXB ameliorates dyslipidemia in ApoE-/- mice." (PMID 41466480, 2025). "Our previous study found that the GLXB herb pair could exert therapeutic effects on dyslipidemia and AS in ApoE-/- mice." (PMID 41466480, 2025). "We propose that in ApoE−/− mice—characterized by severe dyslipidemia and oxidative stress—macrophage AMPK/ULK1 signaling may exist in a primed or sensitized state, rendering it particularly responsive to Cel." (PMID 41347171, 2025). "The benefit of comparing both APOE cKO and D374Y mice is that it allows for broad conclusions as to whether atherogenic dyslipidemia or, rather, gene-specific effects are driving phenotypes." (PMID 39196121, 2024). "The phenotype of FH is also affected by other genes, including ATP-binding cassette subfamily G member 5 (ABCG5), ATP-binding cassette subfamily G member 8 (ABCG8), and apolipoprotein E (APOE), which are known to be causal genes of recessive types of inherited dyslipidemia." (PMID 38540356, 2024). "The abnormal expression of the APOE gene and subsequent dyslipidemia, which could result in an earlier onset of stroke, could be attributed to the hypermethylation of the APOE promoter." (PMID 38255915, 2024). "Although the exact mechanism is yet to be elucidated, it is postulated that APOE ε4 might contribute to the development of metabolic syndrome." (PMID 38509472, 2024). "Establishing the pathogenicity of rare APOE genotypes for FD or other dyslipidemias is complicated." (PMID 39684364, 2024). "The APOE cKO and D374Y mice differed considerably in their initial response to acute atherogenic dyslipidemia, with 35 genes differentially expressed in the APOE cKO and 1,111 genes differentially expressed in the D374Y, as determined by bulk mRNA-seq of the whole liver." (PMID 39196121, 2024). "In contrast, genetic ablation of ApoE in combination with a Western diet (0.2% cholesterol, 21% fat, and 34% sucrose) induced dyslipidemia and increased myofiber damage and fibrofatty replacement in gastrocnemius (GAS) and triceps brachii from a rodent model of DMD." (PMID 37811713, 2023). "Collectively, these data demonstrated that NaB could protect against dyslipidemia in atherosclerotic ApoE−/− mice." (PMID 36888629, 2023). "It was observed that PON1 activity correlated positively with total plasma APOE levels, however this association was present only in patients without metabolic syndrome (MetS), but not in patients with MetS or T2D." (PMID 38084238, 2023). "One study suggested an association between APOE rs429358 genotypes and metabolic syndrome, which became nonsignificant after Bonferroni correction." (PMID 36011277, 2022). "Thus, dyslipidemia developed specifically in ApoE−/− mice, despite them consuming the same 20% fat containing diet as the wild-type mice." (PMID 35208189, 2022). "Many genes such as APOB, LPL, APOA1, LEP, CD36, IL-6, and APOE may play an important role in dyslipidemia." (PMID 36061816, 2022). "ApoE/NOS3−/− mice also inherited the dyslipidemia phenotype of ApoE−/− mice." (PMID 36360235, 2022). "Hyperuricemia and dyslipidemia are associated with left ventricular hypertrophy (LVH), while the effect of ApoE gene polymorphism on the correlation between serum uric acid (UA) level and severity of LVH in patients with coronary heart disease (CHD) has not been clarified." (PMID 36620636, 2022). "For instance, apolipoprotein E (ApoE) deficiency is a common genetic feature in developing CVD due to the inability to maintain cholesterol and triglyceride homeostasis, resulting in dyslipidemia and the formation of atherosclerotic plaques in humans." (PMID 36499091, 2022).
dyslipidemia (continued). "Of the 26 novel APOE variants (not previously reported with dyslipidemia), 12 were missense variants, 5 were synonymous substitutions, 2 were intronic, and 7 were in regulatory regions." (PMID 35628605, 2022). "In a randomized crossover study, participants with metabolic syndrome traits (APOE E3, n = 39; E4, n = 10; mean age, 70 ± 5 years; BMI 31.3 ± 3.0 kg/m2) consumed a Western-like diet high-fat (WDHF), Western-like diet high-carbohydrate (WDHC), or Mediterranean-like diet (MED) meal." (PMID 34836179, 2021). "The present article confirmed that LXJDF could regulate the PI3K/Akt/mTOR pathway to intervene in psoriasis and dyslipidemia comorbidity by the experimental study of LXJDF on the IMQ-induced ApoE−/− mice model." (PMID 33762935, 2021). "Our results could provide robust evidence for preventing and managing dyslipidemia in China’s middle-aged and elderly population, particularly for individualized prevention based on the APOE genotypes." (PMID 34749748, 2021). "Our results could provide useful evidence for preventing and managing dyslipidemia via personalized strategies in China’s middle-aged and elderly population, particularly based on the APOE genotype." (PMID 34749748, 2021). "Both young and aged ApoE-/- mice suffered from dyslipidemia upon HFD intervention as expected." (PMID 33816331, 2021). "Apolipoprotein E (ApoE) is a plasma protein that plays an important role in dyslipidemia." (PMID 34664321, 2021). "Based on this finding, the redox status of serum apoE-Cys thiol may also be involved in disorders of glucose metabolism or accompanying dyslipidemia." (PMID 34286848, 2021). "In view of the fact that the postprandial response is a significant contributor to CVD risk, this study examined for the first time the impact of the APOE genotype (E4 vs. E3) on the postprandial responses of older adults with metabolic syndrome traits to three differently composed meals." (PMID 34836179, 2021). "ApoE-4 carriership might, for example, play a role in dyslipidemia and could thereby contribute to AD pathogenesis." (PMID 32780293, 2021). "Dyslipidemia (p = 0.041, HR = 3.08, 95% I.C. = 1.05: 9.09), age at baseline (p = 0.001, HR = 1.16, 95% I.C. = 1.07:1.27) and ApoE ε4 (p = 0.001, HR = 6.21, 95% I.C. = 2.04:18.9) were statistically significantly associated with an increased likelihood of conversion to AD." (PMID 32485802, 2020). "In addition to ABCB1, we also analyzed variants in APOE and UGT1A7 pharmacogenes, associated with ritonavir induced dyslipidemia and hyperbilirubinemia, respectively." (PMID 33312066, 2020). "The effect of dyslipidemia on progression to AD was confirmed only in ApoE ε4 carriers." (PMID 32485802, 2020). "ApoE ε4 carriers with history of dyslipidemia showed higher risk to convert to AD compared to ApoE ε4− groups and ApoE ε4+ without dyslipidemia patients." (PMID 32485802, 2020). "Unsurprisingly, the proband’s youngest brother (II5) showed no clinical nephrotic syndrome with no abnormalities based on laboratory examination, suggesting that the apoE gene mutation is associated with the pathogenesis of LPG, dyslipidemia and lipoprotein metabolism." (PMID 31092271, 2019).
dyslipidemia (continued). "Induction of APOE was observed in the patients with Porphyromonas gingivalis, which indicated that periodontitis might induce metabolic syndrome via TENM2-activated APOE promoter." (PMID 30547318, 2019). "We developed the KASP technique for the ApoE genotyping, and demonstrated ApoE polymorphisms interacted with smoking/drinking to influence the declining extent of TG, TC and LDL-C levels after statins therapy in Chinese dyslipidemia ASCVD patients." (PMID 31153375, 2019). "Therefore, ApoE−/− mice have been extensively employed as models for metabolic syndrome and NAFLD in recent years." (PMID 30538803, 2018). "Furthermore ApoE is a key regulator of the lipid metabolic processes, participated in the dyslipidemia in aSAH." (PMID 29769126, 2018). "This indicates that dietary SM supplementation does not cause dyslipidemia in high fat-fed apoE-/- mice, which is in agreement with our previous report." (PMID 29240800, 2017). "The model of apoE-/- mice, which develop dyslipidemia and atherosclerotic plaques spontaneously, is devoid of overwhelming metabolic and inflammatory disturbances caused by cholesterol overloading, and is more reliable for studies of mechanisms of the anti-atherosclerotic action of potential drugs." (PMID 28777310, 2017). "In addition, schistosomiasis patients are reported to have dyslipidemia resulting in reduced total cholesterol, LDL and triglycerides when compared to healthy individuals, which depend on apolipoprotein E gene polymorphism." (PMID 28763497, 2017). "The structural differences between the apoE isoforms translate into significant functional changes with implications in pathophysiological conditions including dyslipidemia, cardiovascular diseases, neurodegenerative disorders, infections and inflammatory states." (PMID 28660014, 2017). "Furthermore, dietary intake of E. edulis extract alone or combined with aerobic exercise training was effective in attenuating genetically determined dyslipidemia and steatosis in apolipoprotein E knockout mice (ApoE−/−) fed a normocaloric diet." (PMID 27418954, 2016). "This was confirmed by experimental studies on ApoE−/− mice, where dyslipidemia was associated with increased LV mass in the absence of hemodynamic stress." (PMID 28070143, 2016). "LDL−/− mice have been found to be most suitable for studying the genetics of primary or secondary dyslipidemias, while ApoE−/− mice have been established as the best murine model for characterizing the cytological and molecular aspects of stable and vulnerable plaques." (PMID 27618031, 2016). "In summary, variants that are strongly linked to known forms of dyslipidemia (in APOA5 and APOE), could at most explain only 7 (3.0%) of all 234 affected FCH individuals, thus being of minor importance in our FCH family sample." (PMID 27227539, 2016). "Moreover, the ApoE−/− mice on WD showed a clear dyslipidemia characterised by elevated serum VLDL and LDL cholesterol concentrations." (PMID 26263022, 2015). "Apolipoprotein E-deficient (Apoe−/−) mice are a commonly used mouse model of dyslipidemia, with elevations in non-HDL cholesterol levels and reductions in HDL levels, even when fed a low fat chow diet." (PMID 26555648, 2015). "Rates of four types of dyslipidemia by APOE genotype and by nail selenium quartile groups." (PMID 26380972, 2015). "Thus, the purpose of this study was to investigate the effects of dyslipidemia on osteoclast differentiation and TLR expression in periodontal tissue using an apoE-deficient rat model." (PMID 23295061, 2013). "Therefore, in this study, we observed the possible roles of local RAS activation in dyslipidemia mediated renal injury using ApoE KO mouse." (PMID 23570453, 2013). "Finally, in patients with type 2 DM or dyslipidemia, APOE genotyping may guide dietary and exercise-based interventions." (PMID 41465167, 2025).
dyslipidemia (continued). "Notably, we observed lower T2DM incidence among APOE4+ carriers after adjusting for blood lipids, which could indicate a mechanistic link between APOE-related dyslipidemia and T2DM risk." (PMID 39364911, 2025). "Genetic variations in lipid metabolism genes, such as LPL or APOE, which play a role in lipid homeostasis and vascular function, can be altered by environmental factors such as diet or physical activity, thereby influencing the onset of dyslipidemia and its subsequent vascular consequences." (PMID 41234028, 2025). "In addition, the GLXB herb pair exerted therapeutic effects on dyslipidemia in ApoE-/- mice by increasing the level of butyric acid, a metabolite of the gut microbiota, decreasing the expression of NPC1L1, MTP, ACAT2, and ApoB48 proteins, and inhibiting the intestinal absorption of cholesterol." (PMID 41466480, 2025). "Therefore, we first investigated whether the GLXB herb pair had anti-ApoE-/- mice dyslipidemia effects." (PMID 41466480, 2025). "The p.Gly145Asp variant is associated with dyslipidemia and modifies ApoE towards a more negative isoelectric point that may alter its affinity for the receptor." (PMID 35628605, 2022). "In line with earlier findings, our data confirm the MetS phenotype of agouti KKAy+/–ApoE–/– mice, characterized by hyperglycemia, obesity, and dyslipidemia, as compared with non-agouti KKAy–/–ApoE–/– littermates." (PMID 36505365, 2022). "Generally, ApoE is mainly identified in triacylglycerol-rich lipoproteins to mediate the clearance of their remnants, and it is suggested that an increased ApoE concentration is related to a higher prevalence of metabolic syndrome and premature coronary artery disease." (PMID 35323618, 2022). "Therefore, there are still many aspects of MS pathology in which the contribution of the APOE genotype could be further addressed, such as dyslipidemia related to MS and the possible implications of APOE, its isoforms, and its interacting receptors." (PMID 36153580, 2022). "With the aim of testing whether hidrosmin can effectively affect the development of diabetic renal disease, we induced T1D by STZ injection in ApoE KO mice, a model of combined hyperglycemia and dyslipidemia that develops accelerated renal injury and resembles the morphology seen in DN patients." (PMID 34943023, 2021). "Furthermore, empagliflozin-mediated improvements in endothelium-dependent vasodilation have been noted in a co-morbid rheumatoid arthritis/T2DM rat model, Zucker diabetic fatty rats, metabolic syndrome ZSF1 rats, and in STZ-treated apolipoprotein-E (apoE)-deficient mice." (PMID 34445519, 2021). "Furthermore, we showed that patients who were ApoE ε4 carriers and had history of dyslipidemia showed higher risk to convert to AD both compared to ApoEε4− groups and ApoE ε4+ without dyslipidemia patients." (PMID 32485802, 2020). "Therefore, the phenotype observed in apoE KO mice might results from systemic inflammation driven by dyslipidemia." (PMID 30082772, 2018). "We show that this response is independent of dyslipidemia—a well-known factor promoting systemic inflammation, and previously hypothesized to impact T-cell activity but rather the consequence of apoE deficiency in bone marrow-derived antigen-presenting cells." (PMID 30082772, 2018). "Similarly, in our study, the prevalence of dyslipidemia was 85% in subjects with ApoE-e4 isoforms." (PMID 30026888, 2018). "Interestingly, receptor binding defects for these apoE variants do not correlate well with the severity of dyslipidemia, which can be influenced by other secondary factors." (PMID 22069485, 2011).
dyslipidemia (continued). "The ApoE-mediated mobilization of cholesterol and catabolism of triglycerides is employed in ApoE-/- mice, which rapidly develop CAD induced by dyslipidemia when fed a high-fat diet." (PMID 37242746, 2023). "As for the detection of dyslipidemia in both PCOS-like and obese rats, representative indices such as TG, TC, LDL, ApoE, chemerin, and FFA were increased, while HDL was decreased." (PMID 35436959, 2022). "By establishing an animal model of ApoE−/− mice induced by imiquimod (IMQ), we explored the effects of Liangxue Jiedu formula (LXJDF), a traditional Chinese herb medicine, on psoriasis and dyslipidemia comorbidity through PI3K/Akt/mTOR pathway." (PMID 33762935, 2021). "To study the pathogenesis and pharmacotherapeutics of psoriasis and dyslipidemia comorbidity, we established a composite animal model by applying IMQ on the dorsal skin of ApoE−/− mice." (PMID 33762935, 2021). "The elevated TC, TG, and LDL of ApoE−/− mice reduced under the action of IMQ but were still higher than the control group, showing a phenotype of dyslipidemia." (PMID 33762935, 2021). "Supplement of AceK in HCD worsened the dyslipidemia and increased atherosclerotic plaque, as compared with HCD-fed ApoE−/− mice." (PMID 34836239, 2021). "Finally, given that autophagy deregulation is implicated in many retinal pathologies related to hyperglycemia and dyslipidemia, we investigated if this cellular homeostatic mechanism was activated in FD-fed ApoE-KO mice, once retinal abnormalities were detected." (PMID 33154969, 2020). "In addition to the recognized risk factors of AD, including age, sex, apolipoprotein E4 (APOE Ɛ4) phenotype, and low education level, the influence of metabolic syndrome (Mets) related factors such as hypertension, type 2 diabetes mellitus (T2DM), dyslipidemia on AD has also begun to be emphasized." (PMID 31789604, 2019). "The APOE*3-Leiden(E3L).CETP mouse is a mouse model for human MetS that develops diet-induced dyslipidemia and is prone to develop obesity and insulin resistance." (PMID 29879115, 2018). "The prevalence of dyslipidemia in TC, TG, LDL-C, apoB, and apoE increased with increasing OSA severity (linear trends, p < 0.05)." (PMID 28134311, 2017). "We reported previously the antiatherosclerotic activity of ACE using an apoE knockout mouse model, but the present study is the first to demonstrate a pharmaceutical effect of ACE against metabolic syndrome." (PMID 26508977, 2015). "In conclusion, our novel conditional apoE deletion model has proven here the role of hepatocyte apoE for VLDL production and diet-induced dyslipidemia." (PMID 26695075, 2015). "In conclusion, dyslipidemia induces osteoclast differentiation on the alveolar bone surface by activation of TLR2 and TLR4 in the rat apolipoprotein E knockout model." (PMID 23295061, 2013). "Our aim was therefore to assess the distribution of the APOE, SCARB1, PPARα genotypes in the Lithuanian adult population and to determine the relationship of these genotypes with dyslipidemia." (PMID 23919842, 2013). "The objective of this study was to assess the distribution of the APOE, SCARB1, PPARα genotypes in the Lithuanian adult population and to determine the relationship of these genotypes with dyslipidemia." (PMID 23919842, 2013). "However, the LDL-receptor binding defects for these apoE variants do not correlate well with the severity of dyslipidemia, indicating that these variants may carry additional properties that contribute to their pathogenic potential." (PMID 22069485, 2011).